CD47 (CD47 molecule)
Diseases named in the same sentence as CD47 in open-access papers (continued):
Sharing a sentence is not in itself a finding about the gene and the disease.
tumor (continued). "In xenograft models of multiple patient‐derived solid tumors, treatment with an anti‐CD47 antibody inhibited tumor growth and prevented metastasis, consistent with an effect on CSCs." (PMID 32281289, 2020). "The cluster of differentiation 47 (CD47) molecule is a membrane protein widely distributed on membrane surfaces of various cells, including tumor cells." (PMID 32161718, 2020). "Together, these results suggest that STING-dependent DNA sensing pathway in APCs is essential for its T-cell priming effect in the setting of TMZ and CD47 blockade-induced tumor cell phagocytosis." (PMID 32198351, 2020). "A growing number of studies have since demonstrated that inhibiting the CD47-SIRPα signaling pathway promotes the adaptive immune response and enhances the phagocytosis of tumor cells by macrophages." (PMID 32082311, 2020). "Antibodies blocking the CD47/SIRPα signal pathway can effectively stimulate macrophage-mediated phagocytosis of tumor cells, which becomes a promising approach for tumor immunotherapy." (PMID 31931812, 2020). "There are a lot of data suggesting that the innate immune response plays a fundamental role in modulating tumor phagocytosis through the CD47-SIRPα axis." (PMID 33015199, 2020). "In murine studies of osteosarcoma, CD47 blockade decreased tumor progression, increased macrophage infiltration into the tumor, and increased overall survival." (PMID 33381449, 2020). "Some tumor cell targets are ligands for immune checkpoints (ICPs), such as PD-L1 and CD47, which are the interacting partner for PD-1 and SIRPα, respectively." (PMID 32370812, 2020). "By using the B16F10 mouse model, we compared the in vivo effects of different concentrations of SαV-C-NVs and CD47 mAbs on the inhibition of tumor growth." (PMID 32999291, 2020). "Due to the lower expression of CD47, the tumor accumulation of NPs in group 7 was less than those in group 8." (PMID 32999828, 2020). "CD47 is a transmembrane protein which has recently been characteried as having anti-phagocytic properties which reduce tumor cell immunogenicity." (PMID 33552071, 2020). "In tumor cells, overexpressed CD47 binds signal regulatory protein alpha (SIRPα) on macrophages, resulting in inhibition of myosin accumulation, halting the subsequent phagocytosis." (PMID 33139625, 2020). "Because the overexpression of CD47 in myeloid leukemia cells prevents macrophages from clearing tumor cells, the survival rate of tumor cells increases." (PMID 32161718, 2020). "Another study reported that the therapeutic efficacy of CD47 blockade in tumor models requires DCs to activate adaptive immune responses; DCs, but not macrophages, sense tumor mitochondrial DNA for cross-priming through the CD47–SIRPα signal." (PMID 32536914, 2020). "CD47, the integrin-related protein, plays an important role in immune resistance and escape of tumor cells." (PMID 31931812, 2020). "The importance of CD47 for LSC‐driven tumor formation was demonstrated in a series of xenograft transplantation experiments in which precoating of human AML tumor cells with an anti‐CD47 antibody prevented leukemic engraftment in immunodeficient mice." (PMID 32281289, 2020). "Consistently, PDL1, FASL, TRAIL, and CD47 also co-expressed with Oct4, but were barely detected in somatic tumor cells under in vitro cell culture." (PMID 32218989, 2020). "The interference with CD47–SIRPα interaction synergized with tumor-specific monoclonal antibodies enhanced macrophage-mediated antibody-dependent cellular phagocytosis (ADCP), leading to the elimination of human tumor xenografts in mice." (PMID 32746880, 2020). "After engrafted with CtrlKD or ATP6AP2KD SW620 or DLD1 cells, the mice were treated with a monoclonal antibody blocking CD47-SIRPα interaction, and tumor development was quantified via bioluminescence imaging." (PMID 33603751, 2020).
tumor (continued). "The CD47 role in the tumor and immune system disease also hints at the positive role of CD47 in the proliferation and growth of defective cells, acting as an important player in disease progression." (PMID 32733941, 2020). "As an important “Don’t eat me” molecule, CD47 expressing cells can evade immune surveillance, which was first found in tumor research, and then found to be related to impaired efferocytosis." (PMID 33597922, 2020). "It has become increasingly appreciated that the therapeutic efficacy of CD47 blockade in tumor models requires DCs to activate adaptive immune response." (PMID 32536914, 2020). "Due to its role in tumor angiogenesis, atherosclerotic plaque, and other pathological changes in the formation process, CD47 is a key player in antiangiogenesis." (PMID 32733941, 2020). "aCD47 oriented the M1 Exo to target tumor by bonding to CD47 on tumor cell membranes while the acidic microenvironment cleaved the benzoic-imine bonds to further release aSIRPa and aCD47." (PMID 34123123, 2020). "CD47 is a checkpoint molecule for both innate and adaptive immunity for tumor immune evasion and is thus a promising target for cancer immunotherapy." (PMID 32536914, 2020). "The subcutaneous xenograft model was used to investigate the effects of CD47 on tumor cell growth of CRC in vivo." (PMID 32226539, 2020). "The best characterized therapies targeting this checkpoint are anti-CD47 antibodies, which has proven effective in inducing phagocytosis of tumor cells in vitro as well as inhibiting tumor growth in mice models of both hematologic and solid tumors." (PMID 32012878, 2020). "Therapies that block the interaction of CD47 and SIRPα have been shown to stimulate tumour cell phagocytosis in vitro and induce anti-tumour immune responses in vivo, and CD47 blockade is being tested in clinical trials." (PMID 31205227, 2020). "Treatment of mice with a macrophage-depleting chemical (clodronate) leads to abrogation of the anti-tumorigenic effects of CD47 blockade, supporting the role of macrophages in anti-CD47-mediated anti-tumor response." (PMID 32082311, 2020). "Exosomes engineered with the variant of signal regulatory protein α (SIRPα) antagonise the interaction between CD47 and tumour cells and between SIRPα and macrophages, and increase tumour phagocytosis." (PMID 32276342, 2020). "The experimental results presented here clearly show that RQ promotes TAM polarization toward a more pro-inflammatory M1-like phenotype, down-regulate tumor CD47-SIRPα axis and improve the ICPi effect through macrophage." (PMID 32020472, 2020). "Targeting the CD47–SIRPα axis results in a functional skewing of macrophages toward an M1-like phenotype in tumor models, thus contributing to antitumor immune response, and it has promising clinical prospective in PDAC therapy." (PMID 33505964, 2020). "Here, we show that elimination of CD47, a ligand for the myeloid cell inhibitory receptor SIRPα, from tumor cells by genetic deletion or antibody blocking, significantly improves the effectiveness of the immune response to tumour cells." (PMID 31996683, 2020). "Combining a tumour cell-specific mAb with CD47 blockade has been shown to enhance phagocytosis by providing a pro-phagocytic stimulus through the Fc receptor." (PMID 31205227, 2020). "In order to facilitate the selective binding of anti-CD47 HuNb1 to tumor cells and induce a more powerful antitumor immune response, we established anti-CD47/CD20 bispecific constructs." (PMID 31931812, 2020). "Antitumor mechanisms of the CD47 antibody can be divided into four groups: 1) Enabling phagocytic uptake of tumor cells by macrophages; 2) Promotion of adaptive immunity; 3) Induction of apoptosis; 4) NK cell-mediated ADCC and CDC." (PMID 33469516, 2020). "A differential distribution is demonstrated for CD47 and PD-L1 expression on tumor and immune cells, among peripheral blood and tumor tissue microenvironments." (PMID 32041353, 2020).
tumor (continued). "High level of CD47 regulated tumor initiation, self-renewal, metastasis, and drug resistance in hepatocellular carcinoma 21,22." (PMID 32226539, 2020). "When CD47 in tumor cells binds to SIRPα in myeloid cells, it leads to suppression of tumor cell phagocytosis and other innate immune functions." (PMID 32448366, 2020). "By blocking the CD47–SIRPα pathway, macrophages can rapidly and effectively phagocytize tumor cells, thus promoting tumor inhibition." (PMID 31899582, 2020). "The engineered exosomes expressing SIRPα was able to antagonize CD47 on tumor cells in vitro, and they successively accumulated at tumor sites, inhibiting tumor growth in vivo." (PMID 33374978, 2020). "The data showed that the NK cells and CD8+ T cells in the tumor had significantly lower staining intensity for the CD47-specific antibody than their counterparts in the adjacent healthy tissue (two left panels)." (PMID 32811852, 2020). "Sirpα/CD47 axis blocks phagocytosis, preventing the destruction of self-tissues; however, in the tumor context, the upregulation of CD47 by neoplastic cells represents a mechanism to escape immune clearance." (PMID 32962159, 2020). "IHC staining showed that CD47 was primarily located in the cytoplasmic membrane of tumor cells and to a lesser extent, diffusely in the cytoplasm." (PMID 32043750, 2020). "The increased B7-H3 expression is positively correlated with increased tumor stage, and increased CD47 expression is marginally correlated with increased tumor stage." (PMID 32544882, 2020). "Recent evidence suggests the oncogenic-driven co-expression of CD47 and PD-L1 on tumor cells, which, in co-operation, serve as two-step checkpoints in tumor immune evasion." (PMID 32041353, 2020). "Recent studies revealed that CD47-mediated signals play a vital role in immune-evasion of tumor cells from immune surveillance 15-17." (PMID 32226539, 2020). "CD47 on tumor cells binds to and activates the signal regulatory protein-α (SIRPα), an inhibitory protein expressed on the surface of macrophages, to initiate a signal cascade and inhibit the phagocytic activity of macrophages." (PMID 33224886, 2020). "RQ treatment decreased the expression levels of CD47 and SIRPα on tumor cells and macrophage cells in co-culture experiments." (PMID 32020472, 2020). "Diverse therapeutics, including monoclonal antibodies to CD47 or SIRPα, receptor decoys, and bispecific antibodies that block the CD47-SIRPα axis have demonstrated significant anti-tumor activity in preclinical models of various hematological neoplasms." (PMID 32677994, 2020). "Such an understanding should lead to improvement of CD47-targeted anti-tumor therapeutics able to both neutralize the anti-phagocytic role and trigger autonomous tumor cell death." (PMID 33224442, 2020). "By interacting with CD47, a “don’t eat me” protein, the SIRPα‒CD47 complex blocks the phagocytosis of tumor cells." (PMID 33126572, 2020). "With the addition of newer checkpoints such as B7-H3, CD200R, CD47, and Siglecs 7/9, it seems more logical to combine these checkpoints for synergistic anti-tumor response." (PMID 32117298, 2020). "Previous studies showed that CD47 blockade in tumor models requires DCs to activate adaptive immune responses." (PMID 32536914, 2020). "Flow cytometry performed on 25 patients with Sezary syndrome (SS) showed higher CD47 expression in tumor cells compared with benign T-cells from the same individual." (PMID 32677994, 2020). "CD47 inhibition can also induce apoptosis of tumor cells; for instance, anti-CD47 antibodies increase tumor cell clearance by inducing apoptosis through a caspase-independent mechanism." (PMID 32082311, 2020). "Phagocytosis in response to CD47 blockade elicits an anti-tumour adaptive immune response in the syngeneic A20 model." (PMID 31205227, 2020).
tumor (continued). "There is evidence that TAMs express PD-1, have increased PD-1 expression over time and with higher disease stage, and have a decreased ability to phagocytose PD-L1-expressing tumor cells, lending a rational approach to combination blockade of PD-L1 and CD47." (PMID 35582455, 2020). "Consistently, increased CD47 expression on tumor cells prevents DNA sensing in DCs leading to immune evasion." (PMID 33179413, 2020). "Further, the results suggested that IL-6 derives from tumor-infiltrating macrophages that can induce CD47 expression in HCC by activation of the STAT3 signaling pathway." (PMID 32466488, 2020). "Enhancement of the anti-tumor effects of high-affinity SIRPα-CD47 antibodies obtained when combined with tumor-specific antibodies." (PMID 32677994, 2020). "There is strong preclinical evidence that blocking the CD47-SIRPα interaction with an antibody enhances phagocytosis and restricts the growth of tumors in vivo but whether Shp1 loss in tumor-infiltrating immune cells would similarly enhance anti-tumor immunity remains an open question." (PMID 33133093, 2020). "CD47 has a key role in signaling pathways and appears overexpressed in myeloid malignancies leading to tumor evasion of phagocytosis by macrophages." (PMID 33628731, 2020). "In both solid and hematopoietic mouse tumor models, vaccination with tumor cells or tumor antigen-expressing cells, that lack CD47 or were pre-coated with anti-CD47 antibodies, achieved an antitumor immune response." (PMID 31996683, 2020). "In this work we reported a novel Nb fusion protein HuNb1-IgG4 targeting CD47, showing potent anti-tumor activities and high safety for hematopoietic system in the preclinical studies." (PMID 31931812, 2020). "This review focuses on different therapeutic mechanisms to target CD47, either alone or in combination with other cell surface markers, and its pivotal role in impairing tumor growth and metastatic spread of various types of hematological malignancies." (PMID 32677994, 2020). "Anti-CD47 significantly alters the structure of TAMs in tumor stroma, with a rise in the ratio of M1/M2, simultaneously reconstituting T cells in a more active direction." (PMID 33505964, 2020). "The authors reported that the CD47 blockade in syngeneic mouse model boosted tumor infiltrating T cells activation leading to rapid tumor regression." (PMID 33066447, 2020). "Blockade of the CD47–SIRPα interaction synergizes with tumor-specific antibodies and T-cell checkpoint inhibitors by promoting myeloid-mediated antitumor functions leading to the induction of adaptive immunity." (PMID 33256806, 2020). "In the present study, we sought to determine the role of tumor-intrinsic CD47 signaling in the progression of CRC." (PMID 32226539, 2020). "CD47 is found to be overexpressed on tumor cells and act as a don’t eat me’ signal, which contributes to immune evasion." (PMID 33020240, 2020). "CD47 knockdown impairs the efficacy of pep-20 to induce macrophage-mediated phagocytosis of tumor cells." (PMID 33020240, 2020). "(Hereafter, 5F9), a macrophage immune checkpoint inhibitor, promotes tumor cell phagocytosis by the innate immune response through blocking of the CD47-SIRPα axis." (PMID 32677994, 2020). "Binding of CD47 of tumour binding to SIRPα inhibits the phagocytosis of macrophages to evade innate immunological eradication as well as subsequent adaptive immunity." (PMID 33014356, 2020). "In metastatic BC, CD47 is expressed in the majority of CTCs and is one of the putative markers identifying CTCs with a tumor-initiating capacity." (PMID 32041353, 2020). "Hu5F9-G4, a humanized monoclonal antibody is a macrophage immune checkpoint inhibitor blocking CD47 that induces tumor-cell phagocytosis." (PMID 33202794, 2020). "A more in-depth mechanism of critical anti-tumor immune cells interacting with cancer cells through CD47 needs to be further studied." (PMID 32536914, 2020).
tumor (continued). "In this report, CD47 and PD-L1 were investigated in different stages of tumor progression: early, recurrent, and de novo metastatic BC." (PMID 32041353, 2020). "Pre-clinical data further showed that blockade of the CD47-SIRPα checkpoint on innate cells eventually activates an anti-tumor response in T cells, bridging the innate with the adaptive immunity." (PMID 32983165, 2020). "Accordingly, treatment (i.v.)with anti-CD47 antibodies was effective in various tumor models, with the efficacy largely macrophage-dependent." (PMID 31996683, 2020). "We also demonstrate a differential distribution of CD47 and PD-L1 expression in the blood and tumor tissue microenvironments, highlighting the importance of the peripheral immune response assessment in BC." (PMID 32041353, 2020). "CD47 is expressed on tumor cells and interacts with SIRPα expressed on macrophages to deliver a “don't eat me” signal." (PMID 32625204, 2020). "Upon binding CD47, SIRPα initiates a signaling cascade that results in the inhibition of phagocytosis 189, through which tumor cells can escape from immune surveillance of macrophages and T cells." (PMID 32802188, 2020). "When treated with TMZ plus anti-CD47, a strong tumor growth inhibitory effect accompanied by increased T-cell infiltration was detected in the WT mice." (PMID 32198351, 2020). "As a therapeutic strategy, efforts are underway to block CD47-SIRPα binding and increase the innate immune recognition and phagocytosis of tumor cells." (PMID 35582455, 2020). "CD47 has been indicated to not only play an important role in immune evasion but to also regulate tumor apoptosis, angiogenesis, metastasis, tumor-initiating ability, chemoresistance, and proliferation in many cancers, including HCC." (PMID 32466488, 2020). "The tumor growth in mice that received both anti-CD47 and irradiation was significantly less than that of groups that received either anti-CD47 or focal irradiation." (PMID 31547758, 2020). "Near-infrared photoimmunotherapy has been developed with CD47 antibodies with good local tumor control in vivo." (PMID 35582455, 2020). "If the CD47-SIRPa axis is disrupted by a CD47 antibody, phagocytosis was increased and tumor progression inhibited." (PMID 35582213, 2020). "In immunocompetent syngeneic mice, RCC or melanoma cell tumor formation was markedly suppressed by anti-SIRPα antibody through blockade of CD47 interaction." (PMID 32117298, 2020). "Anti-CD47 antibodies enhance the phagocytosis of tumor cells by macrophages by directly blocking the binding of tumor cell-expressing CD47 to macrophage-expressing SIRPα." (PMID 32082311, 2020). "Another emerging strategy focuses on enhancing innate tumor immunity by targeting the SIRPα-CD47 axis." (PMID 32240171, 2020). "In 2018, a second “don’t eat me” signal was identified, namely the leukocyte immunoglobulin-like receptors subfamily B (LILRBs), which recognize MHC class I molecules on tumor cells and induce resistance to anti-CD47 mAb therapy." (PMID 33121189, 2020). "Our data demonstrate that CD47 signaling can regulate tumor progression in a tumor-intrinsic and immune-independent manner." (PMID 32226539, 2020). "We demonstrate that irradiation or TMZ chemotherapy enhanced anti-CD47 treatment by increasing macrophage-mediated phagocytosis of tumor cell in vitro." (PMID 31547758, 2020). "Dual blockade of CD47 in combination with PD-L1 has also been explored and has shown to enhance immunotherapy against circulating tumor cells." (PMID 32117298, 2020). "Novel methods for specific targeting CD47 and its ligands on tumor cells have been proved in recent studies." (PMID 32677994, 2020). "Researchers have found that there are still some tumor cells escaping from the phagocytosis of macrophages after inhibiting the CD47 molecule." (PMID 32161718, 2020). "Blockade of CD47 with systemically pep-20-D12 treatment also remarkably increased the CD8+ T cell population in tumor tissues." (PMID 33020240, 2020).